TWIST1 (twist family bHLH transcription factor 1)
Diseases named in the same sentence as TWIST1 in open-access papers (continued):
Sharing a sentence is not in itself a finding about the gene and the disease.
tumor (continued). "In order to better understand the relationship between tumor budding, methylation and protein expression of TWIST1 and TWIST2, tumor budding status was divided into low (≤10 buds/10HPFs on average) and high (>10 buds/10 HPFs on average)." (PMID 25528769, 2015). "The results indicate that down-regulation of TWIST-1 reduces tumor growth in vitro and in vivo and this effect is due at least in part to increased cell apoptosis." (PMID 26023795, 2015). "The result showed increased TWIST1 expression in xenograft tumor of MDA-MB-231-Luc shFOXF2 comparing to the control tumor." (PMID 25848863, 2015). "In these studies, CDH1 loss and overexpression of SNAI1, TWIST1 and LAMC2 were observed at the invasive front of the tumors, particularly in single or cords of tumor cells detaching from the tumor mass." (PMID 26214683, 2015). "Consistent with our previous findings in a different tumor model, these results demonstrate that regulation of Bmi1 expression by Twist1 also occurs in the leukemic blasts of AML." (PMID 26832848, 2015). "We also found that TWIST-1 enhanced cell growth, colony formation, drug resistance and tumor formation in AML and CML cell lines." (PMID 26023795, 2015). "The current understanding of the EMT process is that transcription factors including SNAI1, SNAI2, ZEB1, ZEB2 and TWIST1 down-regulate CDH1 expression which subsequently results in the loss of cell adhesion and migration of tumor cells." (PMID 26214683, 2015). "Compared with the primary tumor, the metastatic cell lines showed significantly higher expression levels of miR-183 and Twist1." (PMID 25409297, 2014). "TWIST1's role in tumor formation and progression is an active area of research and its important role is becoming increasingly evident." (PMID 25238494, 2014). "More recently, TWIST1 has been found to be involved in the process of tumor metastasis through the regulation of Epithelial Mesenchymal Transition (EMT)." (PMID 25238494, 2014). "The activity of the oncomiRs/metastamiRs or tumor suppressor miRNAs is regulated by various transcription factors, one of which is TWIST1, which positively regulates the expression of one of the most well-known metastamiRs; miR-10b." (PMID 25426550, 2014). "Results indicated that Twist1/vimentin expression in carcinoma tissues were higher than adjacent non-tumor tissues, and its expression in middle/low differentiation carcinoma tissues higher than high differentiation tissues." (PMID 25144746, 2014). "TWIST1 has been demonstrated to not only affect tumor cell apoptosis, but also promote the invasion and migration of various tumors." (PMID 25289047, 2014). "Obviously, numerous cancer cell lines from various tumor types including breast and lung carcinoma, sarcoma, and neuroblastoma were found to remain dependent on TWIST1 for their survival." (PMID 25566496, 2014). "Reactivation of TWIST1-regulated embryonic programs has been proposed to contribute to tumor progression." (PMID 23555309, 2013). "EMT is a crucial event in tumor progression, and it is associated with dysregulation of DICER1, E-cadherin and miR-200 family, and upregulation of vimentin, N-cadherin, Twist1, Snail and Zeb2." (PMID 23680357, 2013). "TWIST1 promotes tumor metastasis by epithelial-mesenchymal transition (EMT) and formation of invadopodia, the specialized membrane protrusions for extracellular matrix degradation." (PMID 23741524, 2013). "Twist1 also contributes to normal and tumor angiogenesis as well as the epithelial-mesenchymal transition in lung fibrosis and lung cancer, where vascular permeability is increased." (PMID 24023872, 2013). "The EMT inducer TWIST1 promotes tumor development in mice and fosters malignant transformation of human mammary epithelial cells." (PMID 23687063, 2013). "Twist1 is a highly conserved basic helix-loop-helix transcription factor involved in several pathways that control tumor growth, apoptosis, differentiation, and epithelial–mesenchymal transition." (PMID 23349713, 2013).
tumor (continued). "Third, several reports describe a role for Twist1 in the acquisition of resistance to therapeutic drugs, linking Twist to tumor recurrence." (PMID 23967308, 2013). "ZEB1/2 and SNAIs are known to alter E-cadherin mediated cellular adhesion whereas TWIST1 increases tumor seeding resulting in distant metastases." (PMID 23950888, 2013). "TWIST1 induces EMT in tumor cells, and thus plays a dominant role in defining the metastatic potential of primary tumors." (PMID 23555309, 2013). "Forced expression of TWIST1 in ER-MC cells has been reported to produce increased tumor angiogenesis resulting in an aggressive carcinoma phenotype." (PMID 23185544, 2012). "Taken together, our studies suggest that HMGA1 promotes tumor progression through transcriptional networks that facilitate metastatic progression and a stem-like state, at least in part, by inducing the Twist1 and Vimentin, while repressing E-cadherin." (PMID 22276142, 2012). "Considering mRNA and protein information, TWIST1 was positive in only one EGFR wild type tumor (sample 133)." (PMID 22272264, 2012). "For this, we stained 20 tumor tissues with different TWIST1 mRNA expression (n = 10 with high TWIST1 mRNA expression, n = 10 with low TWIST1 mRNA expression)." (PMID 22967435, 2012). "A number of studies showed the important role of Twist1 in promoting cell survival, cell invasion and immigration, and facilitating tumor angiogenesis." (PMID 23133563, 2012). "This mutual dependence of TWIST1 expression on the presence of a notable stromal component and an ER-positive status of the tumor tissue in our and other studies is in line with the observed prognostic value of TWIST1 in ER-positive disease only." (PMID 22967435, 2012). "The high expression of Twist1 in cancers strongly correlates with invasive and metastatic tumor cells." (PMID 22654667, 2012). "There is a growing body of evidence showing that changes in the tumor microenvironment can promote proliferation of the tumor cells and, therefore, can influence outcome of patients, and our data connect this to TWIST1 expression." (PMID 22967435, 2012). "Once in the nucleus, MUC1 acts as a co-activator for the expression of genes linked to tumor cell invasion and metastasis including the EMT-promoting genes TWIST1, SNAI1 and SNAI2." (PMID 22586492, 2012). "In these 20 tumors, TWIST1 mRNA expression levels were significantly correlated with the nuclear protein expression in tumor tissue (Spearman rank correlation, Rs = 0.61, P <0.004)." (PMID 22967435, 2012). "Tumor TWIST1 mRNA expression was higher in patients with >3 positive lymph nodes, and lower in pT2 tumors and in older patients." (PMID 22967435, 2012). "The recovered c-DNA was additionally multiplex tested for three EMT markers [TWIST1, Akt2, phosphoinositide kinase-3 (PI3Kα)] and separately for the tumor stem cell marker ALDH1." (PMID 22264265, 2012). "We observed that 2 out of 7 (29%) of the ER-negative tumor tissues and 10 out of 13 (77%) of the ER-positive tumor tissues showed moderate to strong TWIST1 protein staining in the stroma." (PMID 22967435, 2012). "To further characterize in an unbiased manner the mechanism by which Twist1 suppression was inducing tumor stasis we performed microarray analysis." (PMID 22654667, 2012). "Twist1 encourages cancer cell survival and tumor progression by increasing resistance to cytotoxic therapies resulting in increased cellular proliferation." (PMID 22184289, 2011). "We did not observe significant changes in secreted proteolytic activity in cells overexpressing Twist1, although they gained the ability to invade through Matrigel and metastasize to the lung in a subcutaneous tumor model." (PMID 21725138, 2011). "In both experiments, increased expression of E-cadherin was observed, which suggests that both Twist1 and Sox2 function in harmony and that their concurrence is essential for the maintenance of tumor plasticity." (PMID 22184289, 2011).
tumor (continued). "We detected high Sox2 and Twist1 expression levels in these samples with differential expression in non-tumor areas, suggesting their expression in cancerous tissues and not in normal brain tissue." (PMID 22184289, 2011). "The expression of VIM and TWIST1 increased according to tumor dedifferentiation and was highest in SCK cells (left)." (PMID 21333016, 2011). "Previous reports indicate the role of Twist1 in increased tumor metastatic ability leading to the epithelial-to-mesenchymal transition." (PMID 22184289, 2011). "The recovered c-DNA was additionally multiplex tested for three EMT markers [Twist1, Akt2, PI3Kα] and separately for the tumor stem-cell markers ALDH1." (PMID 19589136, 2009). "If Twist1 regulation via phosphorylation is indeed a critical component of tumor progression, it will provide a potential therapeutic target to inhibit EMT thereby reducing the incidence of lethal pathologies." (PMID 18855684, 2008). "It will be interesting to investigate the role of Twist1 phosphoregulation in the process of tumor progression thus linking the elaborate control of dimer choice and DNA binding preferences to neoplastic disease." (PMID 18855684, 2008). "This study aims to investigate the role and mechanisms of tumor-derived Twist1 in CID." (PMID 40963917, 2025). "Mechanistically, Twist1 drives invasive pseudopod formation through coordinated induction of platelet-derived growth factor receptor α (PDGFRα) expression and Src kinase activation, thereby potentiating tumor cell invasion." (PMID 40530008, 2025). "Numerous studies have shown that targeting Twist1 could significantly inhibit tumor growth, limit tumor metastasis, reverse drug resistance, and thus improve survival rates for cancer patients." (PMID 38415469, 2025). "Twist1, a fundamental helix–loop–helix (bHLH) transcription factor that plays a crucial role in embryonic development and morphogenesis, is highly expressed in various tumour types and serves as a significant regulator of cancer metastasis." (PMID 40344465, 2025). "Tumor-derived EVs may also remodel the local microenvironment of the mPFC, thereby activating Twist1/PPAR-δ signaling pathway." (PMID 40963917, 2025). "In addition, intravenous injection of SDEVs from 4T1 cell tumor-bearing mice increased mRNA and protein expression of Twist1 in the mPFC, which was suppressed when treatment with SDEVs from stable 4T1 cell tumor-bearing mice." (PMID 40963917, 2025). "To verify whether Twist1 mRNA was encapsulated within EVs and protected from RNase A degradation, we treated SDEVs from tumor-bearing mice with RNase A (degrades free RNA) and Triton X-100 (increases cell membrane permeability)." (PMID 40963917, 2025). "Consistent with previous studies 41, 42, Twist1 suppression inhibited tumor growth." (PMID 40963917, 2025). "We observed that knockdown of Twist1 restored PPAR-δ expression in the mPFC of tumor-bearing mice." (PMID 40963917, 2025). "Administration of SDEVs from tumor-bearing mice increased the Twist1 mRNA expression in the mPFC, which could be rescued by knockdown of Twist1 in the 4T1 cells." (PMID 40963917, 2025). "In addition, XLLXF reverses the EMT by increasing E-cadherin expression and decreasing the levels of Vimentin, Twist1, and VE-cadherin, thus preventing tumor cells from acquiring an endothelial-like phenotype." (PMID 41019994, 2025). "Additionally, we performed IHC to evaluate the levels of ECHS1, GCDH, YEATS2, H3K27cr, and Twist1 in HNC tumor and their matched normal tissue sections." (PMID 40810390, 2025). "TWIST2 has tumor-suppressive functions, which is in contrast to the oncogenic role of TWIST1." (PMID 39941895, 2025). "Additionally, the precise mechanism linking Twist1 expression to neuronal dendritic atrophy in the mPFC of tumor-bearing mice remains undefined." (PMID 40963917, 2025).
tumor (continued). "Another important molecule, Twist1, is a conserved basic helix-loop-helix transcriptional factor that is known to activate N-cadherin, which is related to tumor invasiveness; the increased expression of Twist1 is known to be related to tumor progression, invasion, and drug resistance." (PMID 40806148, 2025). "We thus investigated whether Twist1 is necessary for the pro-depressive effect of tumor-derived EVs." (PMID 40963917, 2025). "Furthermore, the observed correlation between elevated Twist1 expression and adverse prognosis in a separate tumor cohort underscores the prognostic value of these EMT markers." (PMID 40362553, 2025). "Strategies to reduce tumor-derived Twist1 should also be explored, as they could both prevent CID and inhibit tumor growth." (PMID 40963917, 2025). "For example, the expression of Twist1 or Snail1 promotes tumor cell extravasation, suggesting that EMT may facilitate both extravasation and initial colonization." (PMID 40530008, 2025). "Twist1 plays a role in tumorigenesis, tumour progression, invasion and metastasis in cancer." (PMID 40344465, 2025). "even pinpointed potential tumor suppressors located on 7p: TWIST1 and SOSTDC1." (PMID 40439002, 2025). "Quantitative detection revealed elevated Twist1 mRNA in SDEVs from tumor-bearing mice." (PMID 40963917, 2025). "For instance, TWIST1 promotes epithelial–mesenchymal transition (EMT) which allows epithelial cells to transform into mesenchymal cells enhancing the ability of tumor cells to migrate from the primary tumor site to secondary tumor sites." (PMID 38791037, 2024). "Our findings illustrate a spatially regulated mechanism by which the vascular niche fuels pro-tumor immunity and suggest that targeting endothelial Twist1 may represent a promising strategy for enhancing the efficacy of T cell–based immunotherapy." (PMID 38416830, 2024). "TWIST1 was also highly expressed by miR-18a/low tumours of both TCGA and METABRIC cohort." (PMID 38786043, 2024). "The expression of Twist1 in tumor cells is modulated by several regulators including signal transducer and activator of transcription 3 (STAT3), nuclear factor kappa B (NF-κB), steroid receptor co-activator 1 (SRC1), Msh homeobox protein (MSX2), and Hypoxia-inducible factor 1-alpha (HIF-1α)." (PMID 38791037, 2024). "Similarly, an inhibitor of TWIST1 signalling had anti‐tumour activity in patient‐derived xenograft models of non‐small lung cancer." (PMID 38650367, 2024). "TWIST1 is part of the highly conserved family of basic helix-loop-helix (bHLH) transcription factors, playing critical roles in various stages of embryonic development and significantly facilitating tumor metastasis and primary tumor growth." (PMID 38575639, 2024). "The identification of potential markers such as MMP9 and TWIST1 in metastatic tumor cells may offer opportunities for early detection and targeted therapies for aggressive cancers." (PMID 38252369, 2024). "A central role Twist1 plays is to suppress the expression of E-cadherin and to promote the expression of mesenchymal-associated proteins including PDGFR-β, MMP-1, and BMI1 in tumor cells, leading to tumor progression and metastasis." (PMID 38416830, 2024). "The animals were sacrificed, and the tumor tissue from stressed animals exhibited increased mRNA expression of the EMT-related genes Twist1, Twist2, Zeb1, Zeb2, Slug, and PLAGL2 and increased protein expression of PLAGL2, Ki67 (a proliferation marker), N-cadherin, and Vimentin." (PMID 38689092, 2024). "Moreover, IHC staining analysis of mouse tumor tissues revealed that VDBP inhibits the expression of VM-related markers induced by Twist1." (PMID 38164156, 2024). "Inversely, silencing of Twist1 expression in CAFs abolishes their tumor-promoting characteristics." (PMID 37143134, 2023).
tumor (continued). "In addition, immunohistochemical (IHC) studies showed that GC-7 treatment robustly inhibited the expression of TWIST1 and BMI-1 proteins, which complied with GC-7-mediated downregulation of eIF5Ahpu levels in xenografted tumor tissues." (PMID 37653021, 2023). "A previous study has reported that p62 could stabilize oncogenic transcription factor TWIST1 which contributed tumor cell proliferation and migration." (PMID 35676831, 2023). "shRNA #1 targeting TWIST1 was excluded, as it leads to extreme suppression of TWIST1 expression, which causes a rare population of migrating cells in 3D environment in vitro and no tumor formation in vivo." (PMID 38092725, 2023). "TWIST1 is a pivotal transcription factor that plays a central role in inducing epithelial-to-mesenchymal transition (EMT), a process closely associated with cell migration and invasion in cancer cells, ultimately promoting tumor progression." (PMID 37748319, 2023). "Group 1 tumor spheroids are highly enriched for programs associated the epithelial–mesenchymal transition, KRAS signaling, and Myc activity and express high levels of the metastasis markers, such as Vimentin, TWIST1, and ZEB2." (PMID 37728504, 2023). "Collectively, JICD1 promotes tumor aggressiveness through TWIST1 in vivo." (PMID 38092725, 2023). "Additionally, a study found a positive correlation between TWIST1 expression and tumor stiffness in patients with breast cancer." (PMID 37916166, 2023). "Our results demonstrate USP29 promotes tumor progression in TNBC through TWIST1." (PMID 36782089, 2023). "The inhibition of TWIST1 reduced JICD1-driven tumor aggressiveness." (PMID 38092725, 2023). "In human non-small cell lung cancer (NSCLC), TWIST1 knockout can inhibit tumor growth." (PMID 37115802, 2023). "Considering that KLF16 is a transcription factor associated with tumor, we hypothesized that KLF16 might regulate Twist1 expression transcriptionally." (PMID 36639679, 2023). "This study also revealed that TWIST1 facilitates EMT and enhances malignant potential by promoting tumor migration, invasion, and cisplatin chemoresistance through the TWIST1-TGFBI-ZEB1 axis in ESCC, highlighting the prognostic and therapeutic potential of TWIST1 in clinical ESCC treatment." (PMID 38001588, 2023). "The functions of Twist1 have been studied in tumor tumorigenesis, stemness, progression, metastasis, and vasculogenic mimicry (VM), which is closely related to the Warburg effect of tumor metabolism." (PMID 37784111, 2023). "In CRC, Twist1 expression is mostly limited to the tumor stroma." (PMID 37143134, 2023). "Moreover, EMT markers (Snail, Slug and Twist1) which are indicative of the metastatic potential in CSCs were high in ALDH+ population of Tumor, but it decreased in the ALDH+ population in T+25." (PMID 38144525, 2023). "Cheng and Zhang reported that Twist1 over-expression could enhance tumor cell proliferation and migration." (PMID 35492076, 2022). "cSCC cells with Twist1 knockdown demonstrate decreased tumor propagating potential." (PMID 35892887, 2022). "The cordycepin group, doxorubicin group and combined group could regulate the EMT process by regulating EMT markers (e.g., N-cadherin, E-cadherin, ZEB1, Twist1) and could inhibit the expression of proteins related to tumor migration." (PMID 35186504, 2022). "A combination of traditional therapeutic modalities with TWIST1-targeted therapy may target the whole tumor mass, including its cancer cells, as well as its CSCs subpopulations, and offer a promising strategy for cancer cure." (PMID 36553636, 2022). "The development of the placenta and tumor growth has very similar characteristics in many aspects, so it can be speculated that the regulatory mechanism of Twist1 on tumor cell apoptosis also acts on trophoblast cells." (PMID 35372470, 2022).